ANKRD33B (ankyrin repeat domain 33B)
Tractability: No criterion of Open Targets' tractability assessment is met for any kind of drug.
Gene: Protein-coding gene on chromosome 5 (10,564,070 to 10,657,816, forward strand). Ensembl gene ENSG00000164236.
Subcellular location (Human Protein Atlas): Mitochondria
Genetic constraint (gnomAD): Loss-of-function variants: 5 observed, 15.41 expected, observed/expected ratio (o/e) 0.32, 90% interval 0.17 to 0.68. The upper end of that interval is the gene's LOEUF score, 0.68, which puts it in group 2 of 6, group 1 being the genes least tolerant of losing a copy. Missense variants: 564 observed, 537.02 expected, observed/expected ratio (o/e) 1.05, 90% interval 0.98 to 1.13. Synonymous variants: 287 observed, 255.03 expected, observed/expected ratio (o/e) 1.13, 90% interval 1.02 to 1.24.
Homologues: Orthologues: chimpanzee ANKRD33B (99% identical), macaque ANKRD33B (95% identical), dog ANKRD33B (78% identical), pig ANKRD33B (78% identical), rat Ankrd33b (76% identical), rabbit ANKRD33B (75% identical), mouse Ankrd33b (74% identical), tropical clawed frog ankrd33b (51% identical), zebrafish ankrd33ba (47% identical), zebrafish ankrd33bb (42% identical). Paralogues in human: ANKRD33 (32% identical), FEM1A (17% identical), FEM1B (16% identical), FEM1C (16% identical).
Diseases named in the same sentence as ANKRD33B in open-access papers:
ANKRD33B is named in the same sentence as 5 diseases in open-access papers, as found by Europe PMC text mining. Sharing a sentence is not in itself a finding about the gene and the disease. The quoted sentences say what the papers report.
inflammatory bowel disease (1 paper, 2017). A spectrum of small and large bowel inflammatory diseases of unknown etiology. "These include an inflammatory bowel disease risk gene ANKRD33B." (PMID 28742084, 2017).
Obesity (1 paper, 2025). Accumulation of substantial excess body fat. "Although ANKRD33B has not been previously linked to any glycaemic traits, variants in this gene have been associated to obesity-related traits." (PMID 40025146, 2025).
infection (1 paper, 2025). The state of being infected such as from the introduction of a foreign agent such as serum, vaccine, antigenic substance or organism. "Knockdown of Snhg15 during VEEV TC-83 infection resulted in the suppression of ten genes including Irf1, Junb, Atf3, Relb, Pim1, Hbegf, Ccl5, Ankrd33b, and H2-K2, all of which were also increased during TC-83 infection when the expression of Snhg15 increased in primary mouse astrocytes." (PMID 40463150, 2025).
tumor (1 paper, 2024). "Among that, the protein expression of IGF2BP3, B2M, CD36, CDKN1A, ANKRD33B, and LHFPL2 were up-regulated; However, the protein expression of APP and CTDSPL was low in both normal and tumor tissues." (PMID 39470474, 2024).
ANKRD33B also shares sentences with these, for which no sentence is quoted: osteosarcoma (1 paper).